INS (insulin)
Diseases named in the same sentence as INS in open-access papers (continued):
Sharing a sentence is not in itself a finding about the gene and the disease.
diabetes (continued). "The effects of AO on insulin sensitivity could be due to its high oleic acid concentration (almost 50%), which facilitates glycemic control in patients with diabetes mellitus." (PMID 35889863, 2022). "However, a significant proportion of patients with diabetes remain on multiple daily insulin injections." (PMID 36013211, 2022). "Insulin remains the most effective drug for treating diabetes mellitus." (PMID 35795141, 2022). "Insulin deficiency (ID) and resistance (IR) contribute to progression from normal glucose tolerance to diabetes to insulin requirement although their relative contributions in young‐onset diabetes is unknown." (PMID 35174618, 2022). "They hypothesized that diabetes duration, disruption to hunger and satiety secondary to exogenous insulin administration and fluctuations in blood glucose increase the risk for DEB in people with T1D." (PMID 35379350, 2022). "Additionally, the findings of this study can contribute to the design and development of glucometers, insulin pumps, and future wearable devices for diabetes care." (PMID 36141360, 2022). "The number of participants receiving insulin or insulin along with OAD increased at 1 year with highest increase in the number of participants taking insulin with OAD was observed in the subgroup with diabetes for >10 years (OAD + insulin: baseline 690/1728 [39.9%] vs. 1 year 809/1667 [48.5%])." (PMID 34856077, 2022). "The importance of nanotechnology in diabetes includes, but is not limited to, inventive diabetes diagnosis, detection of immune cell activity and beta-cell mass, monitoring of glucose level, and non-invasive insulin delivery, etc." (PMID 36289697, 2022). "Diabetes belongs to a group of metabolic disorders that are characterized by a long-term high blood glucose level due to either the inadequate production of insulin (type 1 diabetes mellitus, T1DM) or a poor response of the recipient cells to insulin (type 2 diabetes mellitus, T2DM)." (PMID 36292669, 2022). "However, according to American Diabetes Association (ADA), insulin is the most expensive diabetes treatment in terms of cash price each month, costing more than twice as much as non-insulins." (PMID 35854336, 2022). "This may suggest that S-nitrosylation of PPARγ may be a “bad” modification in diabetes treatment, increases adipocyte production, and impairs insulin sensitivity." (PMID 36551260, 2022). "However, in our study, the success rate was higher and the rate of diabetes was lower and only 9% used insulin after discharge." (PMID 36404508, 2022). "Insulin therapy forms a cornerstone of pharmacological management of diabetes mellitus (DM)." (PMID 35172774, 2022). "The two long-acting insulin analogs (i.e., insulin glargine and insulin detemirere) are produced to cover up the whole day insulin deficiency in patients with diabetes as opposed to the human regular insulin." (PMID 35723344, 2022). "Individual PD1010 is a South Asian man in his 40s born to non-consanguineous parents who was diagnosed with Addison disease in his teens, hypothyroidism and type 2 diabetes mellitus in his 20s (which later became insulin-dependent) and bilateral cataracts requiring surgery in his 30’s." (PMID 35534204, 2022). "Diabetes mellitus (DM) is a chronic disease of the metabolic system related to the insulin hormone." (PMID 36366265, 2022). "Additionally, pathways related to diabetes were also enriched, including the insulin resistance pathway and insulin signaling pathway." (PMID 35592708, 2022). "Has glycemic control improved among US adults with diabetes using insulin over the past 30 years?" (PMID 36538330, 2022). "The previously reported association of insulin with the progression of DR/DME might be due to pre-existing poor diabetes control before the initiation of insulin therapy, possibly owing to the hyperglycemic memory phenomenon." (PMID 35227220, 2022).
diabetes (continued). "Therefore, it is necessary to have other alternatives for the treatment of diabetes mellitus apart from drugs and insulin injection, one of which is to use electrical stimulation with electro-stimulator." (PMID 36465856, 2022). "Similarly, HBE treatment initiated the regulation of glucose by enhancing insulin tolerance capacity in STZ diabetes rats after 120 min of injection with insulin." (PMID 36042748, 2022). "Thus, in diabetes, with low levels of insulin but high levels of glucagon, the increased release of fatty acids forms ketone bodies." (PMID 36128718, 2022). "Insulin has been widely used as a drug to treat diabetes in clinics since it was discovered." (PMID 36430894, 2022). "Diabetes mellitus is a non-communicable disease which is a serious complex multifactorial disorder due to deficiency in insulin secretion or defect in insulin action." (PMID 36616242, 2022). "Insufficient secretion and action of insulin are two important factors leading to IR and diabetes." (PMID 35432468, 2022). "The administration of insulin for diabetes treatment is done subcutaneously." (PMID 36671612, 2022). "For example, the degradation of free fatty acids is thought to impair insulin secretion in β-cell, and may be of particular interest in diabetes; this is an avenue for future research." (PMID 36251711, 2022). "Insulin therapy forms a cornerstone of the pharmacological management of diabetes." (PMID 35172774, 2022). "This is true with the common treatments for diabetes, which include metformin and insulin." (PMID 36555450, 2022). "Insulin therapy was more frequently prescribed in the DKD group (75 vs. 50% in the NDKD group), suggesting either protracted uncontrolled diabetes or that insulin prescription may have biased the classification as DKD by the nephrologist." (PMID 35488507, 2022). "We demonstrate that the addition of exenatide to basal insulin does not further enhance underlying beta-cell function or the capacity to achieve diabetes remission in early T2DM but does yield on-treatment glycemic and weight benefits." (PMID 36244997, 2022). "Therefore, further studies evaluating this marker of insulin sensitivity at diabetes onset are needed to better characterize this interesting feature." (PMID 35139895, 2022). "Age, sex, diabetes duration, and insulin schema were similar between the two groups (all P > 0.05)." (PMID 36204109, 2022). "The plasma insulin in diabetes mellitus and depression group was significantly lower than that in the normal group (P < 0.01), and the glycosylated hemoglobin content increased significantly (P < 0.01), suggesting that the diabetic depression model had been successfully established." (PMID 36072409, 2022). "Derosa, D'Angelo, and Maffioli (2016) showed the role of B. aristata and S. marianum combination in 85 patients with type 1 diabetes mellitus treated with insulin for at least 3 months and subjected to a hypocaloric diet together with increased physical activity." (PMID 35912631, 2022). "Insulin has a strong hypoglycemic action and its discovery by Frederick Banting in 1920 has tremendously paved our understanding of diabetes from the ancient Egyptians and its clinical application was one of the major medical breakthroughs of the twentieth century." (PMID 35397560, 2022). "If ample insulin is not produced in the body diabetes is caused as blood glucose cannot be regulated and remains in the blood." (PMID 36247859, 2022). "The findings in participants with a BMI <25.0 kg/m2 might be due to diminished insulin secretion, which is characteristic of patients with diabetes in Asian countries." (PMID 36726463, 2022). "Women described managing their diabetes as a significant time burden; checking their blood glucose levels, and managing their insulin and meals made it was difficult for some women to find time to express, particularly for those in paid employment or caring for other children." (PMID 34939318, 2022).
diabetes (continued). "The factors contributing to dysglycemia included disease severity, insulin treatment, glucocorticoid use, serum albumin level, total parenteral nutrition, duration of diabetes, elevated procalcitonin level, and need for mechanical ventilation and renal replacement therapy." (PMID 34761326, 2022). "This might be due to increased duration of the disease process, decreased insulin production, incidence of diabetes complications and progressive impairment of insulin secretion." (PMID 36123389, 2022). "Type 2 diabetes mellitus is a metabolic disorder caused by a combination of lifestyle, environmental, and genetic factors, where the cells develop decreased sensitivity to insulin and do not take in the glucose from the blood stream." (PMID 35887304, 2022). "Current therapeutics employed in diabetes are now being tested for their potential effects in preserving beta-cell survival, given that maintaining endogenous insulin secretion—even to a minor degree—may improve clinical outcomes in diabetic patients." (PMID 35115561, 2022). "It seems likely that the relatively high insulin sensitivity that is seen in individuals from this group represents an artifact arising from the ascertainment of those with newly diagnosed, relatively well-controlled diabetes." (PMID 35106505, 2022). "Decreased SMM and strength in diabetics may depend on the duration of diabetes, the use of certain medications such as insulin sensitizers and dipeptidyl peptidase inhibitors." (PMID 35150209, 2022). "Another issue analyzed by the researchers was the assessment of the role of blood pancreatic amylase in the regulation of glucose homeostasis and insulin secretion in a porcine model of streptozotocin- (STZ-) induced diabetes and in a rat pancreatic beta-cell line, BRINBD11." (PMID 35431983, 2022). "Moreover, the earlier systematic reviews have suggested the important role of magnesium supplementation in reducing the magnitude of diabetes‐related complications by regulating glucose levels and insulin sensitivity." (PMID 36249983, 2022). "In this regard, a study with HFD-induced diabetes in mice has already shown that oral administration of the TPH1 inhibitor LP533401 led to an improvement of peripheral insulin sensitivity and glucose tolerance as well as a reduction of hyperglycemia and hyperlipidemia." (PMID 35742878, 2022). "Moreover, recent lines of evidence indicate that chronic hyperglycaemia-induced uncoupling of post-receptor insulin signalling at PI3k-Akt in endothelial cells leads to vascular complications in diabetes." (PMID 35327652, 2022). "Insulin therapy is the gold standard for treating type 1 diabetes mellitus which is caused by a complete lack of this hormone." (PMID 35573427, 2022). "Indeed, the expression of MAFA induced by a Cre-loxP-Rosa system in β-cells of diabetes model mice increased plasma insulin, ameliorated elevated blood glucose and HbA1c, and preserved β-cell function." (PMID 35562869, 2022). "Hence, the objective of the current study was to investigate the direct actions of insulin on the myocardium in diabetes, both in vivo and in vitro." (PMID 35574440, 2022). "As the observed effects are insulin-independent, our model might apply for both types of diabetes, type 1 and type 2, providing a more prospective opportunity for the development of new therapies." (PMID 35806260, 2022). "Interestingly, in the follow-up study conducted 3 years later, insulin levels in the group that developed diabetes after SARS-CoV infection were similar to the healthy population, which suggests that the pancreatic cell damage by SARS-CoV was temporal." (PMID 35769263, 2022). "A lead molecule, JBSNF-000028, was identified that inhibits human and mouse NNMT activity, reduces MNA levels in mouse plasma, liver and adipose tissue, and drives insulin sensitization, glucose modulation and body weight reduction in a diet-induced obese mouse model of diabetes." (PMID 36104373, 2022).
diabetes (continued). "Since type 2 diabetes mellitus (T2DM) is associated with not only insulin resistance but also β-cell dysfunction and impaired insulin secretion, GPR40 has been considered as a therapeutic target for T2DM by increasing insulin secretion." (PMID 36331958, 2022). "We reasoned that compounds that enhance insulin secretion in the setting of β-cell clock disruption might in turn uncover therapeutic targets for more common forms of diabetes mellitus." (PMID 35188462, 2022). "After the development of diabetes, this load may result in a progressive decline in pancreatic beta cell function, thereby necessitating insulin therapy." (PMID 35229479, 2022). "Currently, diabetes is treated with extracorporeal insulin injections." (PMID 36419554, 2022). "Diabetes and insulin resistance could be the consequence of an early, undiagnosed cancer, but, in addition, diabetes could also be related to the precancerous state of the pancreas that affects its insulin-secreting capacity." (PMID 36277886, 2022). "Longer duration of diabetes, high fasting blood sugar level, presence of hypertension, obesity, being on insulin treatment alone), presence of diabetes in a family and poor socio economic status were the most consistent factors associated with the development of DR in diabetic patients." (PMID 35061820, 2022). "Diabetes mellitus (DM) is defined as a metabolic disorder of multiple etiologies characterized by chronic hyperglycemia with disturbance in carbohydrate, protein and fat metabolism resulting from defect in insulin secretion, insulin action or both." (PMID 35578229, 2022). "The Diabetes Control and Complications Trial highlighted the value of rigorous therapy during childhood as it avoids and delays microvascular complications, despite the fact that the first insulin pump was created in the early 1970s." (PMID 36422210, 2022). "Diabetes was managed through diet and in one case by insulin administration (III1)." (PMID 35406570, 2022). "One of the emerged themes was social modelling, where some adolescents used traditional homeopathic medicines such as ginger, cinnamon, and pomegranate peel drinks or even bee stings to substitute insulin, just as their older relatives with diabetes did (Quote #44)." (PMID 38515508, 2022). "Available therapies currently in use for the treatment and management of diabetes include insulin and several oral hypoglycemic agents such as metformin, sulfonylureas, α-glucosidase inhibitors, meglitinide analogues, thiazolidinediones, DPP-IV inhibitors, SGLT-2 inhibitors, and GLP-1 mimetics." (PMID 35807526, 2022). "By contrast, in the second Diabetes Mellitus Insulin-Glucose Infusion in Acute Myocardial Infarction (DIGAMI 2) trial, comprising patients with type 2 diabetes mellitus and acute myocardial infarction (AMI), low MBL was not independently correlated with cardiovascular outcomes." (PMID 35804351, 2022). "After excluding 534 patients with a history of diabetes mellitus, 568 patients with missing data on fasting insulin, fasting glucose and fasting triglyceride, 311 patients lost to follow up at 12-months, 1226 nondiabetic acute ischemic stroke patients were included in this analysis." (PMID 35260102, 2022). "Diabetes mellitus (DM) is a metabolic disorder characterized by high blood glucose levels and alterations in the metabolism of carbohydrates, fats, and proteins, resulting from defects in insulin action and/or secretion." (PMID 35669587, 2022). "Insulin sensitizers represent a new type of therapeutic drug for diabetes patients." (PMID 35502441, 2022). "Although the demand for insulin will increase in the later stages of diabetes, in our study, we found that there were significant differences in the treatment of each diabetes cluster at different stages of diabetes." (PMID 36457559, 2022).
diabetes (continued). "The proposed wines could be a good alternative type of wine, with an increased polyphenol content and the potential to control the insulin response supporting therapy for diabetes." (PMID 37431046, 2022). "Where there is a lack of reasonable adjustments to care, inflexible services, inadequate provision of diabetes education or negative attitudes from professionals, people with intellectual disabilities have more difficulty achieving optimal diabetes management with insulin." (PMID 35983585, 2022). "Accordingly, recently, controlled studies in humans, as well meta-analysis reviews of studies in humans, have shown several positive actions of high-protein diets in patients with diabetes, including improved glycemic control, improved insulin sensitivity, and reduced body adiposity." (PMID 35409318, 2022). "In addition to technologies used to track general health measures, various devices for glucose monitoring and insulin delivery can help improve glycemic control in patients with diabetes." (PMID 34922811, 2022). "A patient with diabetes uses an insulin pump to dose insulin." (PMID 36502149, 2022). "Elucidation of the implication of the β-cell dedifferentiation phenomenon in clinical intensive insulin therapy may result in the development of preemptive medical care for patients with diabetes." (PMID 35562869, 2022). "These hypotheses all center around the concept of increased insulin resistance, cytokines and other inflammatory mediators, lipid storage, and how obesity stimulates diabetes at the molecular level." (PMID 36012526, 2022). "The butyrate-mediated secretion of glucagon-like peptide-1 may mediate the reduction of insulin sensitivity and diabetes." (PMID 36016798, 2022). "Researchers rarely used these tolerance tests to diagnose diabetes but were interested in various glucose metabolism indicators calculated from the glucose and insulin levels during the tests, including AUC, insulin : glucose ratios and glucose disappearance rate." (PMID 35504844, 2022). "Defective production of insulin in pancreatic β-cells or impaired insulin action as a result of genetic condition or even secondary to other metabolic complications are considered the key features of diabetes." (PMID 36290794, 2022). "However, the pathophysiology of diabetes is very different between American and Asian people; Asian people exhibit a low insulin secretion ability and insulin resistance with mild obesity." (PMID 35115614, 2022). "Diabetes especially type II, is generally the predominant metabolic disorder occurring globally and is extremely diverse with fluctuating degrees of oxidative stress, insulin resistance and pancreatic β-cell dysfunction." (PMID 36532555, 2022). "Insulin injection and oral hypoglycemic medications are the traditional treatments for diabetes." (PMID 36339446, 2022). "Automated Insulin Delivery (AID) systems represent an important advance in diabetes therapy." (PMID 36992765, 2022). "Type 2 diabetes mellitus (T2DM) results from the body's ineffective use of insulin." (PMID 35656460, 2022). "Symptoms and patient features (body mass index, excessive urination, polydipsia, the dynamics of weight gain/loss, the existence of auto-antibodies as well as ketones, and levels of C-peptide) have a role in the control of diabetes mellitus and insulin therapy." (PMID 36187456, 2022). "In diabetes mouse models, Sam68 levels in the liver are drastically upregulated, contributing to the hyperglycemia; the ablation of hepatic Sam68 lowers blood glucose level and improves insulin sensitivity." (PMID 36232770, 2022). "We found that paternal use of some of the non-insulin anti-hyperglycemic agents was related to certain adverse outcomes, and we cannot rule out that these associations are caused by diabetes itself, or uncontrolled disease, rather than the drug." (PMID 36362820, 2022).